COMT (catechol-O-methyltransferase)
Diseases named in the same sentence as COMT in open-access papers (continued):
Sharing a sentence is not in itself a finding about the gene and the disease.
melanoma (5 papers, 2010 to 2025). A malignant, usually aggressive tumor composed of atypical, neoplastic melanocytes. "One of the retrieved publications concerned in vitro studies in which the effect of UVB on COMT activity in melanoma cells was assessed." (PMID 38067245, 2023). "Searching for the words “COMT” and “melanoma” in the title or abstract for the last 20 years reveals five publications." (PMID 38067245, 2023). "The highly methylated environment in human melanoma cell lines (e.g., SkMel-28) has been reported, and both COMT (Cathechol O-methyl transferase) and DNA methyltransferase-1 were found to be increased approximately five and eight times, respectively." (PMID 21079799, 2010). "The study showed the presence of COMT in both melanoma cells and keratinocytes." (PMID 38067245, 2023). "This study also tested the hypothesis that certain drugs used in the treatment of PD (L-DOPA, MAO-B and COMT inhibitors, and amantadine), aimed at increasing dopamine concentration, could potentially contribute to the development of melanoma." (PMID 38067245, 2023). "The assumed search criteria for publications indicate that the topic of the relationship between treatment with COMT inhibitors for PD and the risk of melanoma has not been widely discussed in the literature." (PMID 38067245, 2023). "Furthermore, the addition of the COMT inhibitor, tolcapone, reduced melanin levels in melanoma cells parallel to reduced cell numbers." (PMID 38067245, 2023). "However, this study shows that under in vitro conditions, COMT activity is an important factor that stimulates melanin synthesis in melanoma cells." (PMID 38067245, 2023). "Medication variables associated with melanoma risk were ever use of a dopamine agonist (HR, 1.18; 95% CI, 1.01–1.38) and ever use of a COMT inhibitor (HR, 0.76; 95% CI, 0.58–0.99) compared with no use." (PMID 35224798, 2022). "Research has shown that miR-493-5p knockout significantly changed the role of NR2F1-AS1 in the occurrence and progression of melanoma, while the miR-493-3p/HNRNPU/COMT/Dopamine axis may be related to melanocyte imbalance in the pathogenesis of segmental vitiligo." (PMID 40211852, 2025).
memory impairment (5 papers, 2018 to 2025). "Another example is the COMT gene (Catechol-O-Methyltransferase), whose SNPs have been associated with lower chances of developing memory impairment and higher odds of developing distal neuropathic pain." (PMID 34444495, 2021).
myocardial infarction (5 papers, 2007 to 2025). Gross necrosis of the myocardium, as a result of interruption of the blood supply to the area, as in coronary thrombosis. "Low-activity catechol-O-methyltransferase (Comt) prevents myocardial infarction and reduces its risk." (PMID 39863867, 2025). "Opposite results were reported, in which the low activity genotype of COMT reduced the risk of myocardial infarction." (PMID 30011860, 2018). "The catechol-O-methyltransferase (COMT) gene contains a functional polymorphism, Val158Met which has been related to common diseases like cancer, psychiatric illness and myocardial infarction." (PMID 17577421, 2007). "The possible mechanism behind the protective effect of the low activity COMT genotype on myocardial infarction is not fully understood." (PMID 30011860, 2018).
ovarian carcinoma (5 papers, 2009 to 2025). A malignant neoplasm originating from the surface ovarian epithelium. "The aim of the present study was to examine the relationship of the COMT Val158Met polymorphism to disease by comparing polymorphism expression in patients with ovarian cancer and healthy controls." (PMID 33389924, 2021). "This study is the first to investigate the relationship between ovarian cancer and the Val158Met polymorphism in the COMT gene in a Turkish population." (PMID 33389924, 2021). "The aim of the present study was to examine the relationship between COMT Val158Met polymorphism and the risk of ovarian cancer." (PMID 33389924, 2021). "Therefore associations between COMT gene variations and ovarian cancer risk should be investigated in larger sample sized studies in a Turkish population." (PMID 33389924, 2021). "Thus, our study aim to provide reliable data about the role of COMT Val158Met polymorphism in ovarian cancer due to these uncertain results." (PMID 33389924, 2021). "In addition, the presence of SNPs in CYP1B1 and COMT that increase both the formation of depurinating estrogen-DNA adducts and the likelihood of ovarian cancer (six-fold) supports an ER-independent mechanism of cancer initiation by estrogens." (PMID 34361004, 2021). "Heterozygote COMT Val158Met genotype could have possible effect on ovarian cancer by reducing activity of phase II enzyme that decrease the elimanition of carcinogens." (PMID 33389924, 2021). "The women with two copies of both the low-activity COMT allele plus the high-activity CYP1B1 allele demonstrated much higher values of the DNA adduct ratio, and the odds ratio for ovarian cancer was 6-fold higher compared to women with the normal-activity alleles of the enzymes." (PMID 30854528, 2017). "Neither the COMT variant nor the CYP1A1 rs4646903 variant were statistically significantly associated with ovarian cancer risk on meta-analysis (data not shown)." (PMID 19127255, 2009). "Neither the COMT variant nor the CYP1A1 rs4646903 variant were associated with the risk of ovarian cancer on meta-analyses of the published literature and the OCAC data." (PMID 19127255, 2009). "There are two meta-analyses perfomed in order to determine the role of COMT Val158Met polymorphism in ovarian cancer susceptibility and both of them could not find any associations." (PMID 33389924, 2021).
panic disorder (5 papers, 2011 to 2022). An anxiety disorder characterized by multiple unexpected panic attacks with persistent concern of recurring attacks. "In a meta-analysis of 363 datasets, ADHD and panic disorder proved to be associated with the G (Val) allele of rs4680 (COMT) among whites." (PMID 36661490, 2022). "One of the most studied and supported gene with multiple results is COMT Val158Met polymorphism, especially in female panic disorder patients." (PMID 31435520, 2018). "Prevalence of the more active COMT allele has been related to panic disorder, in particular in female patients, whilst low COMT activity has been associated with increased risk of chronic pain syndromes." (PMID 21845158, 2011). "The COMT val allele has previously been shown to be associated with increased amygdala activation during processing of aversive stimuli such as fearful faces in healthy probands as well as in patients with panic disorder." (PMID 22745815, 2012).
Stroke (5 papers, 2014 to 2022). Sudden impairment of blood flow to a part of the brain due to occlusion or rupture of an artery to the brain. "Given the links between dopamine level and dysphagia, and the association of the COMT SNPs with motor recovery after a stroke, we considered the possibility that COMT Val158Met polymorphism would affect swallowing function and responsiveness to NIBS." (PMID 35330487, 2022). "In a recent study, Val/Val phenotype showed greater improvement in Fugl-Meyer Assessment and Functional Independence Measure score at 3 and 6 months after stroke, indicating that dopamine-related COMT polymorphism may affect motor recovery after stroke." (PMID 35330487, 2022). "Evidence linking variations in the gene for COMT to differences in motor skill outcome in stroke patients, given regular physical therapy treatment, suggests that baseline “dopaminergic tone” is one factor in recovery." (PMID 30034335, 2018). "COMT is known to influence working memory, motor learning, and swallowing, and rs4532 of DRD1 is reported to affect post-stroke swallowing recovery in the elderly." (PMID 35330487, 2022).
Abdominal obesity (4 papers, 2017 to 2025). Excessive fat around the stomach and abdomen. "In addition, COMT expression is significantly reduced in obese mice fed a high-fat diet, and low activity of the COMT allele is associated with abdominal obesity." (PMID 39810946, 2025). "Contrary to this, low activity COMT (Met/Met or Val/Met) was associated with acute coronary events in Finnish men (n = 792), and with high systolic and diastolic blood pressure and abdominal obesity in Swedish men (n = 1302)." (PMID 30045690, 2018).
adenomyosis (4 papers, 2022 to 2024). The growth of endometrial tissue inside the muscular wall of the uterine corpus. "Cytochrome P450 (CYP) genes and catechol-O-methyltransferase (COMT) gene variants could increase the risk of an estrogen-dependent disease like adenomyosis." (PMID 37763670, 2023). "COMT polymorphism may contribute to the risk of EMs and adenomyosis and has a relationship with EM susceptibility." (PMID 35350240, 2022). "Moreover, COMT 158 G/A gene polymorphisms contribute to the high risk of adenomyosis, particularly in Asian populations, further supporting the role of polymorphisms of estrogen metabolism genes in human adenomyosis." (PMID 35887822, 2022). "Moreover, COMT 158 G/A gene polymorphisms contribute to the high risk of adenomyosis." (PMID 37763670, 2023). "Studies have found that the variants of the Cytochrome P450 (CYP) gene and catechol-O-methyltransferase (COMT) gene affect enzyme activity and promote estrogen-dependent diseases, including adenomyosis." (PMID 39201621, 2024). "A line of evidence found that cytochrome P450 (CYP) genes and catechol-O-methyltransferase (COMT) gene variants could influence enzyme activity and increase the risk of estrogen-dependent diseases, such as adenomyosis." (PMID 35887822, 2022).
alexithymia (4 papers, 2014 to 2025). An agnosia that is a deficiency in understanding, processing, or describing emotions. "Concerning the Val108/158Met polymorphism of the COMT gene, the Val carriers are the individuals with a higher risk of alexithymia." (PMID 39202385, 2024). "The present study revealed the possible influence of COMT polymorphism on the correlation between alexithymia and hypervigilance to pain." (PMID 34948872, 2021). "Future studies with a larger sample size and a wider participant age range are thus necessary to confirm the influence of COMT polymorphism on the correlation between alexithymia and the PVAQ." (PMID 34948872, 2021). "Therefore, we investigated whether the correlation between alexithymia and hypervigilance to pain is influenced by COMT polymorphism in healthy individuals." (PMID 34948872, 2021). "Therefore, this study investigated whether COMT polymorphism influences the correlation between alexithymia and pain, assessed by the TAS-20 and PVAQ, respectively." (PMID 34948872, 2021). "Alexithymia has been linked to specific polymorphisms of the catechol O-methyltransferase and serotonin transporter genes, suggesting that genetically based individual differences in monoamine systems of importance for emotional processing could be one factor underlying alexithymia." (PMID 25076933, 2014). "The main candidate genes associated with alexithymia are from the serotoninergic pathway (SLC6A4, HTR1A and HTR2A) and neurotransmitter metabolism (DRD2/ANKK1, COMT, BDNF, and OXTR)." (PMID 39202385, 2024). "This indicated that COMT polymorphism does not affect the psychometric properties of hypervigilance to pain and alexithymia." (PMID 34948872, 2021). "The results revealed a significant positive correlation between the “difficulty describing feelings” of the 20-item Toronto Alexithymia Scale and the “attention to changes in pain” of the pain vigilance and awareness questionnaire in COMT Met carriers but not in Val/Val individuals." (PMID 34948872, 2021).
behavioral disorders (4 papers, 2020 to 2025). "Research indicates that the COMT gene is linked to an increased risk of behavioral disorders and mental illnesses, as structural changes in the prefrontal cortex are associated with this gene." (PMID 41595431, 2025). "Other COMT SNPs have also been studied in association with psychopathic traits and related behavioral problems." (PMID 35163702, 2022). "Available data show genetic variations in the catechol-O-methyltransferase (COMT) gene that are associated with several traits of psychiatric and behavioural disorders, including PTSD and aggression." (PMID 35205345, 2022).
concussion (4 papers, 2018 to 2026). A concussion, also known as a mild traumatic brain injury (mTBI), is a head injury that temporarily affects brain functioning. "This interaction, however, was not explored in the studies included in our review, which focused instead on the independent effects of the COMT rs4680 polymorphism on cognition across brain injuries." (PMID 41476008, 2026). "The genes of particular interest for their potential effect on event-related potentials are Apolipoprotein E, Catechol-O-methyltransferase, and Dopamine Receptor D2, as they have been previously suggested to influence concussion susceptibility and cognitive function." (PMID 29910309, 2018). "Specifically, studies could be done regarding the COMT and DRD2 as potential candidate genes in relation to concussion, as previous studies have linked these genes to significant anomalies in cognitive function and ERP components." (PMID 29910309, 2018). "Neurotransmission-related genes (BDNF, COMT, DRD1–3, DBH, SLC6A4, HTR2A, APOE) influenced motivation, fatigue, cognitive performance, and brain injury recovery." (PMID 41596414, 2026). "Nevertheless, epistasis analysis identified a genetic interaction of COMT (rs4680) and MAPT (rs10445337) G-C alleles as more common in elite rugby athletes, and carriage of these variants may affect stress resilience, behavioural traits and altered risk of concussion incidence and severity." (PMID 35627205, 2022).
conduct disorder (4 papers, 2015 to 2025). A disorder diagnosed in childhood or adolescence age group characterized by aggressive behavior, deceitfulness, destruction of property or violation of rules that is persistent and repetitive, and within a one year period. "Over the last decade, several candidate genes (i.e., MAOA, DRD4, DRD2, DAT1, 5-HTTLPR, and COMT) have been extensively studied as potential moderators of the detrimental effects of postnatal family adversity on child externalizing behaviors, such as aggression and conduct disorder." (PMID 26537239, 2015).
deafness (4 papers, 2017 to 2020). An inherited or acquired condition characterized by the complete loss of the ability to hear from one or both ears. "Based on these data, it was speculated that TOMT acts as a catechol O-methyltransferase in vivo, and that the deafness phenotype of the mouse mutant was caused by hair-cell degeneration resulting from a failure to properly metabolize catecholamines." (PMID 28534737, 2017). "We did not include the SNPs in the following genes: ACYP2 (coding for an acylphosphatase), SLC31A1 gene coding for the copper transport protein 1, SLC22A2 coding for the organic cation transport protein 2, megalin, TPMT and COMT and Mendelian deafness gene." (PMID 30112115, 2018).
eating disorder (4 papers, 2005 to 2023). A broad group of psychological disorders with abnormal eating behaviors leading to physiological effects from overeating or insufficient food intake. "Prior studies have uncovered a potential connection between COMT polymorphisms and eating disorder pathology." (PMID 37511777, 2023).
endometriosis (4 papers, 2012 to 2025). The growth of functional endometrial tissue in anatomic sites outside the uterine body. "Polymorphisms in CYP17A1, a key enzyme in estrogen biosynthesis, and COMT, which regulates the metabolism of catechol estrogens, have been linked to altered local estrogen homeostasis and increased susceptibility to endometriosis." (PMID 41462999, 2025). "Five Mendelian randomization methods indicated that both AGPAT4 and COMT could serve as risk genes for endometriosis." (PMID 38850428, 2024). "Our investigation identified 11 genes associated with endometriosis risk, with AGPAT4 and COMT emerging as pivotal biomarkers through machine learning analysis." (PMID 38850428, 2024). "Several SNPs of the estrogen synthesis- and metabolism-related genes, such as CYP19, CYP1A1 and COMT, and CYP1B1, have been found to be associated with increased risk of endometriosis." (PMID 23139742, 2012). "Interestingly, our study did not reveal significant expression of COMT, another gene previously implicated in endometriosis, suggesting a more prominent role for AGPAT4 in the disease’s pathogenesis." (PMID 38850428, 2024).
Headache (4 papers, 2011 to 2026). Cephalgia, or pain sensed in various parts of the head, not confined to the area of distribution of any nerve. "The role of the catechol-O-methyltransferase (COMT) Val158Met rs4680 polymorphism in altered pain processing in headaches is controversial." (PMID 42278631, 2026).
insomnia (4 papers, 2020 to 2024). A sleep disorder characterized by difficulty in falling asleep and/or remaining asleep. "Notably, two loci COMT (catechol-O-methyltransferase) and CCDC68 (coiled-coil domain containing 68) have previously been associated with sleep disturbance and insomnia." (PMID 33192958, 2020). "Regarding the different adverse events, an inverse correlation of COMT was noted in relation to constipation, insomnia, dry mouth, dry skin, lack of appetite, red skin, and nervousness (probability > 90%)." (PMID 37240556, 2023).
Insulin resistance (4 papers, 2017 to 2024). Increased resistance towards insulin, that is, diminished effectiveness of insulin in reducing blood glucose levels. "Also, both genetic and pharmacologically-induced deficiency of COMT exacerbates high-fat diet (HFD)-induced insulin resistance in mice." (PMID 31877978, 2019). "Experimental and clinical data link reduced COMT activity and 2ME levels to the development of obesity and insulin resistance." (PMID 31877978, 2019). "An increase in the insulin level and insulin resistance was found in the COMT siRNA-treated mice compared with control mice." (PMID 28801594, 2017).
irritable bowel syndrome (4 papers, 2011 to 2023). Irritable bowel syndrome (IBS) is a chronic functional condition of the lower gastrointestinal (GI) tract characterized by abdominal pain or discomfort and disordered bowel habit (diarrhea, constipation, or fluctuation between the two). "The Met allele of a genetic polymorphism (Val158Met) in the catechol-o-methyltransferase gene (COMT) was associated with increased placebo responses in patients with irritable bowel syndrome." (PMID 25222607, 2014). "We hypothesized that the COMT functional val158met polymorphism, was a predictor of placebo effects and tested our hypothesis in a subset of 104 patients from a previously reported randomized controlled trial in irritable bowel syndrome (IBS)." (PMID 23110189, 2012).
Nephropathy (4 papers, 2015 to 2024). A nonspecific term referring to disease or damage of the kidneys. "A decrease in genetically predicted COMT plasma abundance was causally associated with an increased risk of T2DM nephropathy and coma, aligning with the causal direction between COMT and T2DM." (PMID 39280009, 2024). "Association of COMT gene with diabetes and nephropathy has been reported in a study conducted in the Asian Indian population in which a genetic variant showed association for diabetic nephropathy." (PMID 25969822, 2015). "Additionally, the association of common biochemical and clinical parameters was assessed for this COMT polymorphism with diabetes and nephropathy in Pakistani Punjabi population." (PMID 25969822, 2015). "However, no colocalization evidence was found between COMT and T2DM nephropathy and coma, despite high support of colocalization between COMT and T2DM." (PMID 39280009, 2024). "Interestingly, it has found that entacapone exhibits its anti-inflammatory properties through anti-oxidation and anti-inflammatory mechanisms in Ang II-induced kidney damage, rather than changes in renal dopaminergic tension induced by COMT inhibition." (PMID 34017338, 2021).